MRPL38 (mitochondrial ribosomal protein L38)
Synonyms: L38mt; MRP-L38; HSPC262; RPML3; MRP-L3; MGC4810; mL38
Tractability: Small molecule: a structure with a bound ligand is known. PROTAC: ubiquitination databases record sites on it; its protein half-life has been measured.
Target class: Other cytosolic protein
Gene: Protein-coding gene on chromosome 17 (75,898,643 to 75,905,093, reverse strand). Ensembl gene ENSG00000204316.
Subcellular location: Mitochondrion
Subcellular location (Human Protein Atlas): Mitochondria
Pathways (Reactome):
Metabolism of proteins: Mitochondrial ribosome-associated quality control; Mitochondrial translation elongation; Mitochondrial translation initiation; Mitochondrial translation termination
Gene Ontology:
Molecular function: protein binding
Biological process: mitochondrial translation
Cellular component: mitochondrial large ribosomal subunit; mitochondrion; mitochondrial inner membrane
Genetic constraint (gnomAD): Loss-of-function variants: 51 observed, 49.22 expected, observed/expected ratio (o/e) 1.04, 90% interval 0.83 to 1.31. The upper end of that interval is the gene's LOEUF score, 1.31, which puts it in group 5 of 6, group 1 being the genes least tolerant of losing a copy. Missense variants: 527 observed, 504.19 expected, observed/expected ratio (o/e) 1.05, 90% interval 0.97 to 1.12. Synonymous variants: 245 observed, 206.06 expected, observed/expected ratio (o/e) 1.19, 90% interval 1.07 to 1.32.
Gene-disease validity (ClinGen):
ClinGen rates the evidence that MRPL38 causes each of these diseases.
mitochondrial disease (autosomal recessive): Limited.
Homologues: Orthologues: chimpanzee MRPL38 (96% identical), macaque MRPL38 (95% identical), pig MRPL38 (88% identical), mouse Mrpl38 (87% identical), guinea pig MRPL38 (85% identical), dog MRPL38 (84% identical), rabbit MRPL38 (84% identical), rat Mrpl38 (77% identical), tropical clawed frog mrpl38 (59% identical), zebrafish mrpl38 (51% identical), Drosophila melanogaster mRpL38 (35% identical), Caenorhabditis elegans mrpl-38 (28% identical). Paralogues in human: PEBP1 (17% identical), PEBP4 (12% identical).
Diseases named in the same sentence as MRPL38 in open-access papers:
MRPL38 is named in the same sentence as 6 diseases in open-access papers, as found by Europe PMC text mining. Sharing a sentence is not in itself a finding about the gene and the disease. The quoted sentences say what the papers report.
liver cancer (3 papers, 2019 to 2025). An epithelial or non-epithelial malignant neoplasm that arises from the liver. "This provides genetic evidence for the potential role of MRPL38 in liver cancer, with its variation potentially affecting the risk of liver cancer development." (PMID 40371222, 2025). "Exon sequencing was performed on liver cancer samples using next-generation sequencing technology, the results indirectly proved that MRPL38 was highly expressed in liver cancer." (PMID 33238645, 2020).
ovarian carcinoma (2 papers, 2021). A malignant neoplasm originating from the surface ovarian epithelium. "The relevance of mL38 (MRPL38) to cancer prognosis has been highlighted in ovarian cancer, by comparing the mitochondrial proteomic profile of human ovarian carcinoma cell lines with different metastatic potentials." (PMID 34071057, 2021). "Additionally, MRPL38 and MRPL49, among other MRPs, were confirmed to be significantly related to the invasion and prognosis of ovarian cancer." (PMID 33934540, 2021).
colorectal cancer (1 paper, 2024). A primary or metastatic malignant neoplasm that affects the colon or rectum. "Likewise, in colorectal cancer, analysis of genes associated with metastasis found that MRPL38 was associated with lower levels of metastasis through SLC25A10." (PMID 39354291, 2024). "MRPL38 is associated with fewer metastatic lesions in both lung and colorectal cancers." (PMID 39354291, 2024).
cancer (2 papers, 2021 to 2024). A tumor composed of atypical neoplastic, often pleomorphic cells that invade other tissues. "It is possible that EMILIN3 and MRPL38 are not directly involved in the development of drug resistance in cancer; the fact that we were unable to find any information in the literature linking them to drug resistance reinforces this hypothesis." (PMID 38443409, 2024). "MRPL38, EMILIN3 and RALYL are overexpressed in non-resistant cancer cell lines." (PMID 38443409, 2024).
MRPL38 also shares sentences with these, for which no sentence is quoted: cognitive decline (1 paper); liver neoplasm (1).